INS (insulin)
Diseases named in the same sentence as INS in open-access papers (continued):
Sharing a sentence is not in itself a finding about the gene and the disease.
Insulin resistance (continued). "In addition, since those phenotypes precede the onset of insulin resistance and BW gain, it follows that glucose intolerance, increased blood glucose, and plasma insulin, and the further worsening of the feeding control develop in parallel to BW gain in this animal model." (PMID 37819196, 2023). "Although it has been shown that, with the onset of puberty, insulin sensitivity decreases and insulin concentrations increase, the authors showed that girls with early menarche continued to maintain hyperinsulinemia and/or insulin resistance throughout puberty." (PMID 37836591, 2023). "This association has been studied in males, where Ang II was found to increase phosphorylation of IRS-1 and inhibit insulin-stimulated activation of eNOS, suggesting that Ang II may be the link between insulin resistance and the development of vascular cell dysfunction." (PMID 38025203, 2023). "Moreover, catecholamines may contribute to insulin resistance by stimulating the overexpression of glucose transporters at the renal level, resulting in increased insulin secretion." (PMID 37512517, 2023). "Therefore, improving insulin clearance may be crucial to the attenuation of insulin resistance and glucose intolerance." (PMID 36675244, 2023). "Moreover, endothelial FABP4 promotion of lipolysis-mediated insulin secretion may be detrimental for β cell health and function, since hyperinsulinemia is a driver for the development of insulin resistance." (PMID 37279064, 2023). "In addition, it has been found that Rb1 can improve metabolic disorders in high-fat diet-induced obese mice related to gut microbiota regulation, and oral administration of Rb1 significantly reduces serum LDL-c, TG, insulin, and insulin resistance index (HOMA-IR) in high-fat diet (HFD) mice." (PMID 37049846, 2023). "In addition, FMT from butyrate-treated donors tended to decrease fasting plasma levels of glucose (–11%, P = 0.07) and insulin (–25%, P = 0.07) and markedly reduced homeostatic model assessment of insulin resistance (HOMA-IR) (–32%, P < 0.05) in recipient mice." (PMID 36810253, 2023). "The purported mechanisms for HCV-induced insulin resistance include, but are not limited to: direct viral effects on the downregulation of glucose transporters and release of pro-inflammatory cytokines leading to changes to the insulin signalling pathway, as well as promoting hepatic steatosis." (PMID 37325792, 2023). "There were great differences in insulin resistance and components of MS or beta-cell function between patients with IAs-related hyperinsulinemia and real hyperinsulinemia; the former group had worse beta-cell function, and the latter was more insulin resistant." (PMID 37324170, 2023). "We previously discovered that PC-derived S100A9 could induce insulin resistance by inhibiting insulin-stimulated glucose uptake in muscle cells and thereby led to PCDM, a paraneoplastic phenomenon occurring in approximately 50% of PC patients within 24 months before the diagnosis of cancer." (PMID 37280516, 2023). "Growing evidence suggests that brain insulin signaling, other than having a role in the regulation of cerebral metabolism, regulates key molecular pathways involved in mood, behavior, and cognition, that are impaired following development of brain insulin resistance." (PMID 36670973, 2023). "IL-34 was found to significantly inhibits insulin-stimulated glucose transport in human differentiated adipocyte, which may explain its role in insulin resistance and making it a suitable marker to reflect insulin resistance status in T2DM patients." (PMID 37072577, 2023). "In addition, relative hyperinsulinemia in the impaired ketogenesis group might be due not only to insulin resistance but also to lower hepatic insulin clearance, which has been previously reported to be associated with MAFLD." (PMID 36896171, 2023).
Insulin resistance (continued). "Furthermore, due to damage to AKT1 signaling pathways, insulin cannot be effectively transported to the vascular system by the action of endothelial nitric oxide synthase (eNOS), leading to obesity and insulin resistance, followed by artery dysfunction and hypertension." (PMID 37664830, 2023). "Moreover, insulin is essential for controlling the activity of lipolysis in adipose tissue, which is dysregulated in insulin resistance and results in the release of significantly elevated amounts of FFAs, pro-inflammatory cytokines (IL-1, IL-6, and TNF-), and glycerol into the bloodstream." (PMID 36977005, 2023). "In addition, a high level of insulin is common in patients with insulin resistance, and this may play a role in sodium and urate retention at more distant sites along nephrons." (PMID 36904083, 2023). "In individuals with normal insulin sensitivity, sustained glucagon suppression was seen with lower insulin concentrations compared to individuals with insulin resistance, and glucagon is thus not suppressed to the same extent for high insulin concentrations in individuals with insulin resistance." (PMID 36752854, 2023). "HOMA-IR (HOmeostatic Model A assessment for Insulin Resistance) is calculated as follows: serum fasting insulin × glycemia/22.5 (for glucose concentration in mmol/L) or serum fasting insulin × glycemia/405 (for glycemia in mg/dL; in both cases, insulin concentration is in mU/mL)." (PMID 37509329, 2023). "However, we and others have recently called this hypothesis into question, and the causal relationship between changes in early insulin signaling and the downstream actions of insulin remains unclear, especially in the context of insulin resistance." (PMID 36808134, 2023). "Notably, in our cohort, AA subjects showed lower levels of insulin and insulin resistance." (PMID 37628669, 2023). "In addition, some subtypes of adipose-derived ceramidases could desensitize insulin activity and contribute to insulin resistance." (PMID 37274346, 2023). "Adipose tissue insulin resistance may be particularly important in promoting ectopic fat deposition as the reduced ability of insulin to suppress adipose tissue lipolysis, or prompt lipogenesis, leads to the increased delivery of non-esterified fatty acids (NEFA) to ectopic sites." (PMID 37491534, 2023). "Besides, the liver could regulate insulin efficacy through removing 50% of secreted insulin in peripheral circulation, inhibiting hyperinsulinemia induced insulin resistance in adipose/muscle tissues." (PMID 37817192, 2023). "Thus, impaired insulin secretion and insulin resistance in skeletal muscle could be characteristic of underweight individuals with higher GV indices, resulting in postprandial hyperglycemia." (PMID 37792730, 2023). "Insulin resistance is accompanied by hyperinsulinism, which increases the levels of free androgen in the plasma by reducing the production of sex hormone-binding globulin, and high levels of androgen and insulin in the plasma can affect endometrial cell differentiation." (PMID 36964546, 2023). "As it predicted a reduced insulin secretion independent of insulin resistance, CRP might be associated with or lead to reduced islet beta-cell function in women after GDM." (PMID 37891561, 2023). "In addition, patients with cachexia often have insulin resistance or decreased insulin secretion, which may be due to the fact that the body prevents insulin from playing its anti-lipolysis role in CAC." (PMID 37205195, 2023). "This raises questions regarding whether the glucose phenotype observed in WD + STZ mice is solely attributed to impaired endogenous insulin secretion or if it is also influenced by peripheral insulin resistance related to elevated circulating insulin levels due to WD feeding." (PMID 37885804, 2023).
Insulin resistance (continued). "Insulin resistance (IR) is a condition in which tissues are not responding properly to insulin, and it has been identified as a major cause of numerous diseases, including type 2 diabetes (T2DM), cardiovascular diseases (CVD), polycystic ovary syndrome (PCOS), and dyslipidemia." (PMID 37946276, 2023). "In all 29 subjects, the fasting insulin levels and HOMA-IR were positively correlated with the PBMCs' mitochondrial OXPHOS capacity with complex I + II-linked substrates, indicating a relationship between insulin resistance and increased mitochondrial oxidative metabolism in PBMCs." (PMID 36997629, 2023). "For example, hyperinsulinemia, which is associated with insulin resistance in T2DM may increase SNS activity that worsens the cardiovascular complication, and the direct effect of insulin on promoting postganglionic symN activity using cultured rat SCG symNs has been demonstrated." (PMID 37229433, 2023). "Furthermore, mice with adipose tissue-specific knockout of Glut4 mRNA have abnormal glucose tolerance and insulin resistance, even though the expression levels of insulin signaling-related factors in other tissues were comparable to those of wild-type healthy mice." (PMID 36902049, 2023). "Although insulin resistance increases the risk of Alzheimer's disease (AD), the mechanisms remain unclear, partly because no animal model exhibits the insulin‐resistant phenotype without persistent hyperglycemia." (PMID 37822109, 2023). "There is also evidence to suggest that insulin increases hepatic IGF-1 and IGFBP-3 production through direct regulation of the GH receptor, and thus, in patients with severe insulin resistance, IGF-1 deficiency may be due to both impaired hepatic production and accelerated IGF-I excretion." (PMID 36331627, 2023). "Due to pubertal insulin resistance affecting even healthy adolescents, eating carbohydrates earlier in the day (via breakfast) when insulin sensitivity and glucose tolerance are highest may be particularly important for this population, placing less demand on the pancreatic β-cells." (PMID 37513628, 2023). "Dysregulated secretion of GH, autoimmune beta cell destruction, impaired insulin secretion, increased insulin resistance, hyperglucagonemia, and an impaired incretin axis have all been hypothesized to be the primary or major physiological mechanism(s) contributing to hyperglycemia in TS." (PMID 36875465, 2023). "Furthermore, leptin secretion is stimulated by increased insulin levels, which could be a contributing mechanism in the present study for women with slight insulin resistance." (PMID 37731394, 2023). "We also investigated whether activation of brain insulin signaling or inhibition of insulin receptor signaling, as occurs in brain insulin resistance, could impact insulin BBB transport by delivering insulin or the selective insulin receptor antagonist S961, directly to the brain." (PMID 37076875, 2023). "It is widely thought that the diminution of first-phase insulin secretion is the earliest detectable defect of pancreatic β-cell function in individuals at high risk for T2DM; this defect largely represents β-cell exhaustion after years of compensation for antecedent insulin resistance." (PMID 37242267, 2023). "Considering its wide distribution in nephron segments, it has been possible to identify insulin in animal models, in which IRs are diminished in insulin resistance states, thereby allowing the determination of the degree of importance in normal and pathological states related to insulin resistance." (PMID 37675359, 2023). "As mentioned, augmented SUA levels may lead to oxidative stress, which then may impair glucose metabolism and reduce insulin sensitivity, and might contribute to insulin resistance by upregulating insulin receptor substrate 1 phosphorylation, as well as increased production of excessive ROS." (PMID 37671195, 2023).
Insulin resistance (continued). "However, it predicted a reduction in the relative or insulin-resistance-adjusted insulin secretion." (PMID 37891561, 2023). "In addition, it has been found that exposure to phthalates may reduce insulin levels in fetal rats, which may lead to insulin resistance in adulthood." (PMID 37325320, 2023). "However, the measurement of glycemia or insulin alone could underestimate the prevalence of insulin resistance in this population of BC survivors." (PMID 37106164, 2023). "Indeed, aging results in the defenestration of liver sinusoidal endothelial cells, which in turn may impair insulin clearance, resulting in hyperinsulinemia and hepatic insulin resistance." (PMID 37059838, 2023). "Similarly to our observations, decreased SHBG mRNA and protein levels have been previously correlated to lower expression of insulin-associated effectors, namely, IRS-1, IRS-2, PI3Kp85α and GLUT-3 and GLUT-4, and has been further linked to the PI3K/AKT pathway-mediated systemic insulin resistance." (PMID 38146533, 2023). "Furthermore, S100A11 was nonlinearly correlated with FPG, FPI, HOMA-IR, hepatic ISI, WBISI, and CIR in patients with IGT and DM, suggesting that S100A11 is involved in insulin resistance, pancreatic β-cell function, and hepatic and whole-body insulin sensitivity." (PMID 36872321, 2023). "More importantly, accumulating evidences demonstrated that the obese animals and humans who displayed leptin resistance may directly contribute to the suppression of lipid oxidation in insulin-sensitive organs and ultimately lead to accumulation of lipids and insulin resistance." (PMID 37114144, 2023). "This could also suggest that immune cells deficient in Slc7a11 might not be able to induce insulin resistance as effectively, although the intrinsically lower insulin secretion does not support this hypothesis." (PMID 37650924, 2023). "Furthermore, higher levels of blood glucose and insulin (as seen in the WD offspring) may be indicative of insulin resistance." (PMID 37447184, 2023). "Persons of younger ages have also been found to present with severe form of the disease along with complication such as obesity, higher degrees of insulin resistance and rapidly increasing blood glucose which may explain the high use of insulin in this group compared to sulphonylurea medications." (PMID 37315063, 2023). "However, increased levels of advanced glycosylation end-products or direct effects of exogenous insulin, with pathologically high levels of insulin in a background of insulin resistance, might also have a role." (PMID 35976428, 2023). "According to studies conducted on diabetic patients, curcuminoids enhance insulin resistance, decrease levels of leptin, resistin, interleukin (IL)-6 IL-1β, and tumor necrosis factor-α, increase the release of adiponectin, and decrease glucose and insulin levels." (PMID 37240220, 2023). "On the other hand, the development of insulin resistance is associated with two main processes, the first through the increase in serum lipids and the second through the increase in key enzymes of gluconeogenesis and glycogenolysis (G6P and PKC), leading to an increase in insulin concentration." (PMID 36875280, 2023). "However, it predicted a reduction in insulin resistance-adjusted insulin secretion (ISSI-2)." (PMID 37891561, 2023). "In addition, our previous studies verified that the activation of PPARγ could alleviate obese insulin resistance with the IRS-1 insulin metabolic pathway in vivo and in vitro." (PMID 37049846, 2023). "Furthermore, 10 mg/kg ginsenoside CK could also alleviate hyperglycemia and insulin resistance in db/db mice by regulating skeletal muscle insulin sensitivity." (PMID 38137182, 2023). "However, hyperinsulinemia itself can further induce insulin resistance over time because constant exposure to insulin triggers a negative feedback loop, which causes insulin receptors to become less responsive to insulin and downregulate." (PMID 37446104, 2023).
Insulin resistance (continued). "However, a recent study found that TAC impacts both insulin secretion and insulin resistance." (PMID 37151651, 2023). "Since insulin resistance results in a reduced ability of insulin to block muscle protein breakdown after a glucose load, increased circulating glutamine levels might depend on the higher release of this amino acid into the circulation as a consequence of impaired blockade of protein breakdown." (PMID 36677056, 2023). "Insulin resistance is a condition in which the biological effect of insulin on target tissues is impaired, the efficiency of promoting glucose uptake and utilization is reduced, and the body compensates by producing excess insulin to produce hyperinsulinemia and maintain blood glucose stability." (PMID 37073893, 2023). "Moreover, our results suggested that TAC-induced impairment of hepatic insulin signaling (manifested as decreased levels of GLUT2, IRS2 and pAKT) might cause the insulin resistance observed in patients with NODAT." (PMID 37151651, 2023). "Moreover, in the male population, S100A11 levels could predict β-cell function after adjusting for insulin resistance and considering the degree of insulin sensitivity." (PMID 36872321, 2023). "Because skeletal muscle is the major site of insulin-stimulated glucose disposal, effects of disturbed iron homeostasis on glycemia might be expected, and mitochondrial dysfunction in muscle is a hallmark of T2DM and insulin resistance." (PMID 36137277, 2023). "The CD mice in our study demonstrated the lowest levels of insulin, which may be partly explained by the high soy content of the CD; soy consumption has been shown in some studies to discourage insulin resistance in mice and humans, though this theory has been disputed." (PMID 37447184, 2023). "Furthermore, metformin improved insulin resistance and reduced endogenous insulin production." (PMID 36779088, 2023). "Studies on rodent models have displayed that insulin resistance may result in a reduction in surface dopamine transporters and reduced insulin-dependent dopamine release in the striatum, giving an explanation of higher motor progression and dopamine-transporter deficit found in T2DM patients." (PMID 37895336, 2023). "On the other hand, increased MF through resistance training promotes increased insulin sensitivity, which also affects the risk of MetS, a possible mechanism through which high MF may influence insulin resistance is by stimulating proteins in the insulin-signalling cascade." (PMID 36443504, 2023). "Thus, a low SHBG level may reflect the degree of existing insulin resistance, while androgen excess might impair post‐prandial insulin secretion." (PMID 36484476, 2023). "Metformin works by improving insulin resistance, decreasing the hepatic production of glucose by inhibiting gluconeogenesis and by an action on glucose-6-phosphatase, decreasing glycaemic values and also enhancing the effect of insulin on muscular glucose absorption." (PMID 36983739, 2023). "The absence of Prx6 causes both reduced insulin secretion and increased insulin resistance." (PMID 37298303, 2023). "Moreover, in the late stages of disease progression, beta cell failure could lead to insulin resistance and reduced blood insulin levels." (PMID 38012280, 2023). "Because insulin’s physiological functions such as carbohydrate intake and metabolism, glucose synthesis, and lipid metabolism are no longer as effective, increased insulin levels are essential to achieve adequate metabolism function in individuals with insulin resistance." (PMID 36984594, 2023). "On the one hand, SGLT-2 inhibitors can improve insulin resistance, increase glucose excretion in urine by competitively blocking sodium–glucose co-transporter in the renal proximal convoluted tubules, reduce insulin level, improve insulin resistance and reduce stimulation of fat regeneration." (PMID 37254186, 2023).